HOXD8 (homeobox D8)
Diseases named in the same sentence as HOXD8 in open-access papers:
HOXD8 is named in the same sentence as 37 diseases in open-access papers, as found by Europe PMC text mining. Sharing a sentence is not in itself a finding about the gene and the disease. The quoted sentences say what the papers report.
breast carcinoma (9 papers, 2014 to 2024). "LINC00969 inhibits the proliferation with metastasis of breast cancer by regulating the phosphorylation of PI3K/AKT through HOXD8/ILP2." (PMID 38130932, 2023). "In breast cancer, high expression of HOXD8 suppressed the proliferation, metastasis, and invasion of breast cancer by inhibiting the ILP2 expression." (PMID 37827698, 2023). "It has been reported that ILP-2, which is highly expressed in breast cancer, can inhibit the expression of HOXD8 in breast cancer tissues and cell lines through certain pathways." (PMID 35814477, 2022). "Enforced expression of HOXD8 in breast cancer repressed tumor growth by inactivating AKT/mTOR pathway." (PMID 36387262, 2022). "Furthermore, ILP-2 knockout could reverse the effects of HOXD8 knockdown on breast cancer cell proliferation, invasion, and migration." (PMID 35814477, 2022). "For example, the knockdown of Homeobox D8 (HOXD8) can enhance the expression of Phosphoinositide 3-kinase (PI3K) and phosphorylated Ak Strain Transforming (p-AKT) proteins in breast cancer cells." (PMID 38822408, 2024). "For example, miR-196a has been studied for its oncogenic roles in glioblastoma, pancreatic adenocarcinoma, breast cancer, oesophageal adenocarcinoma, and colorectal cancer, and shown to target HOX family genes (HOXA7, HoxB7, HOXC8, HOXB8, HOXD8), ERG, HMGA2, ANXA1, S100A9, SPRR2C, KRTS." (PMID 24621885, 2014).
colorectal cancer (7 papers, 2014 to 2024). A primary or metastatic malignant neoplasm that affects the colon or rectum. "Overexpression of HOXD8 in colorectal cancer cells impaired cell proliferation and migration via inducing apoptotic event." (PMID 36387262, 2022). "HOXD8 was found to be downregulated in colorectal cancer and functioned as a tumor suppressor in colorectal cancer progression." (PMID 29367650, 2018). "Also, HOXD8 has been identified as a downstream target of miR-196a, and it was found that the expression level of HOXD8 was downregulated in colorectal cancer tissues." (PMID 38302924, 2024). "In colorectal cancer, miR-196a inhibited the expression of HOXA7, HOXB8, HOXC8 and HOXD8 genes, leading to AKT pathway activation and increased cell motility." (PMID 29259267, 2017). "HOXD8 is a vital member of the HOX gene family, and its expression in colorectal cancer tissues is decreased, leading to the inhibition of malignant behavior in colorectal cancer cells." (PMID 38130932, 2023).
lung carcinoma (6 papers, 2019 to 2024). "Downregulation of miR-142-5p leads to upregulation of HOXD8 and caused drug resistance in lung cancer cells." (PMID 34497755, 2021). "Specifically, HOXD8 is epigenetically downregulated in lung cancer and used as a biomarker to detect prostate cancer in urine samples." (PMID 35177798, 2022). "We identified 7 DMRs corresponding to 7 differentially methylated genes (DMGs) including HOXB4, HOXA7, HOXD8, ITGA4, ZNF808, PTGER4, and B3GNTL1 that were highly associated with lung cancer by comparing the methylation profiles of lung cancer and benign nodule tissue." (PMID 37101220, 2023). "It turned out that the expressions of B3GNTL1 and HOXD8 were significantly upregulated, while the expression of remaining five genes (HOXB4, ZNF808, ITGA4, PTGER4, and HOXA7) were significantly downregulated in lung cancer tissues (p < 0.01)." (PMID 37101220, 2023). "In addition to HOXA9, the methylation of HOXB4, HOXD8, and HOXD9 were also different between tumor and adjacent normal tissues in lung cancer." (PMID 31850197, 2019).
bladder cancer (4 papers, 2020 to 2024). "Thereafter, we continued to investigate the mechanism whereby LINC01116 regulated HOXD8 in bladder cancer." (PMID 33311496, 2020). "LINC01116 could regulate ELK3 and HOXD8 to promote bladder cancer cells proliferation, migration, and invasion." (PMID 37424068, 2023). "In sum, LINC01116 recruited DKC1 to stabilize the mRNA of a tumor-promoter HOXD8 in bladder cancer." (PMID 33311496, 2020). "In the context of bladder cancer, LINC01106 has been found to influence ELK3 and HOXD8 at the post-transcriptional level, thereby accelerating the disease’s advancement." (PMID 38255219, 2024). "Some studies have suggested that HOXD8 has tumor suppressive functions in hepatocellular carcinoma and CRC, while others have suggested that it can act as a tumor promoter in ovarian cancer and bladder cancer." (PMID 38263157, 2024).
biliary tract cancer (3 papers, 2022 to 2024). "Hypermethylation of a CpG island located in the promoter of HOXD8 (chr2:176,993,479–176,995,557) is a validated biomarker of biliary tract cancer." (PMID 38336771, 2024). "Hypermethylation of HOXD8 is used as a biomarker to detect biliary tract cancers." (PMID 37245199, 2023).
neuroblastoma (3 papers, 2012 to 2019). Neuroblastoma (NB) is the most common solid, extracranial childhood tumor. "We recently identified an RA-HOXD8-HOXC9 axis in driving neuroblastoma cell differentiation:38–40 RA induces HOXD8, which, in turn, transcriptionally activates HOXC9 expression." (PMID 30631055, 2019). "In neuroblastoma, however, the HOX genes have been linked to differentiating cells and specifically HOXD1 identified here (as well as HOXC6 and HOXD8) are associated with differentiation towards a neuronal phenotype." (PMID 29757368, 2018). "Previous studies have revealed a marked induction of HOXD1 and HOXD8 following RA treatment in several human neuroblastoma cell lines examined including SK-N-BE, CHP-134, SK-N-SH, LA-N-1 and LA-N-5." (PMID 22879880, 2012). "We further present evidence that HOXC9, also a key mediator of RA action in neuroblastoma cells, is a direct target gene of HOXD8." (PMID 22879880, 2012). "Together, these findings demonstrate distinct functions of HOXD proteins in regulation of neuroblastoma cell proliferation, with only HOXD3, HOXD8, HOXD9, HOXD10 and HOXD12 proteins being able to recapitulate the G1 arrest phenotype induced by RA." (PMID 22879880, 2012). "HOXD8 directly activates the transcription of HOXC9, a key effector of RA action in neuroblastoma cells." (PMID 22879880, 2012). "In this study, we show that individual induction of HOXD8, HOXD9, HOXD10 or HOXD12 in neuroblastoma cells is able to recapitulate RA-induced differentiation phenotype." (PMID 22879880, 2012). "Notably, the four human HOXD proteins (HOXD8, HOXD9, HOXD10, HOXD12) with both anti-growth and differentiation-inducing activities in neuroblastoma cells correspond to the Drosophila Hox proteins abd-A (HOXD8) and Abd-B (HOXD9, HOXD10, HOX12) that are responsible for specifying the abdomen." (PMID 22879880, 2012).
ovarian carcinoma (3 papers, 2018 to 2024). A malignant neoplasm originating from the surface ovarian epithelium. "We postulated that HOXD8 is a transcription factor associated with cisplatin resistance and metastasis of ovarian cancer." (PMID 30194340, 2018). "Transcriptional factor Homeobox D8 (HOXD8) is significantly overexpressed in patients with recurrent ovarian cancer when compared to patients with primary malignant tumors and is associated with cisplatin resistance and metastasis in the advanced disease." (PMID 39458997, 2024). "HOXD8 gene expression should be further assessed together with other potential biomarkers and epigenetic regulators to improve ovarian cancer diagnosis and treatment." (PMID 30194340, 2018). "The patients with recurrent ovarian cancer had higher expression of HOXD8 than patients with primary malignant tumours (p = 0.02) or benign tumours (p = 0.001)." (PMID 30194340, 2018). "In 52 cases of different ovarian disease, the patients with recurrent and cisplatin-resistant ovarian cancer had higher expression levels of HOXD8 than patients with primary malignant tumours (p = 0.018, p = 0.001) or benign tumours (p = 0.001, p < 0.001)." (PMID 30194340, 2018). "Moreover, the expression of HOXD8 was increased in the serum samples of patients with recurrent ovarian cancer." (PMID 30194340, 2018). "Powered replication studies in homogeneous cohorts of ovarian cancer patients treated with standard cisplatin-based chemotherapy will enable a better understanding of the prognostic and predictive relevance of HOXD8 gene expression as a potential biomarker of cisplatin-resistance and metastasis." (PMID 30194340, 2018).
glioma (2 papers, 2015 to 2025). A benign or malignant brain and spinal cord tumor that arises from glial cells (astrocytes, oligodendrocytes, ependymal cells). "The upregulation of HOXA9, HOXC6, HOXC11, HOXD1, and HOXD8 expression is associated with the proliferation and growth of glioma." (PMID 26565624, 2015). "Since MAPK6, HOXD8, and PSMB1 all belong to gene families with important roles in glioma, they remain considered targets for future evaluation as canine-specific drivers of HGO." (PMID 42135822, 2025). "There were several DEGs that were overexpressed in the French bulldogs that are not specifically implicated in glioma but belong to important gene families with known roles in glioma, including SCN11A, MAPK6, HOXD8, and PSMB1." (PMID 42135822, 2025).
colon cancer (1 paper, 2022). "The role of posterior HOXD genes in colon cancer is not well defined; HOXD8 and HOXD12 expression are reduced in colon cancer, whereas HOXD10 expression may be increased." (PMID 35015732, 2022).
esophageal squamous cell carcinoma (1 paper, 2013). Esophageal squamous cell carcinoma (ESCC) is a type of esophageal carcinoma (EC) that can affect any part of the esophagus, but is usually located in the upper or middle third. "Deregulated expression of HOX genes including HOXB8, HOXC8, HOXD8 and HOXA7 in esophageal squamous cell carcinoma have been reported, and miR-196a is significantly up-regulated in pancreatic, breast, and esophageal cancer." (PMID 23967217, 2013).
leukemia (1 paper, 2015). A malignant (clonal) hematologic disorder, involving hematopoietic stem cells and characterized by the presence of primitive or atypical myeloid or lymphoid cells in the bone marrow and the blood. "We further confirmed that MEIS1 and HOXB7 or MEIS1 and HOXD8 combinations are genuinely synergistic in leukemia induction." (PMID 26606454, 2015). "HOXB7 and HOXD8 are new partners of MEIS1 that have never been reported to have leukemia-inducing potential prior to this study." (PMID 26606454, 2015).
liver cancer (1 paper, 2020). An epithelial or non-epithelial malignant neoplasm that arises from the liver. "MiR-5692a plays the role of an oncogene in the occurrence and development of liver cancer by regulating the expression of HOXD8." (PMID 33490103, 2020).
lymphoma (1 paper, 2021). A malignant (clonal) proliferation of B- lymphocytes or T- lymphocytes which involves the lymph nodes, bone marrow and/or extranodal sites. "Increased methylation of HOXD8 was observed in lymphoma patients compared to normal B cells." (PMID 34944472, 2021).
migraine (1 paper, 2023). "HOXD8 is a gene playing important role in different cancers but its involvement in migraine aetiology is unclear." (PMID 37245199, 2023).
Obesity (1 paper, 2017). Accumulation of substantial excess body fat. "The homeobox gene, HOXD8, and the HOX-related long-noncoding RNA, HOTAIRM locus, may also warrant further investigation with regard to the dysfunction of adipose tissue in severe obesity, as DMRs in these two loci were only observed in the before weight loss comparison." (PMID 28473875, 2017).
papillary thyroid cancer (1 paper, 2021). "HOXA-AS2 regulated the HOXA-AS2/miR-520a-3p/homeobox D8 and mitogen-activated protein kinase kinase kinase 2 axis in non-small lung cancer 46, and the miR-15a-5p/homeobox A3 (HOXA3) axis in papillary thyroid cancer." (PMID 33754013, 2021).
tumor (19 papers, 2009 to 2025). "Of the eight HOX genes, the mRNA and protein levels of HOXD8 were downregulated in ccRCC than that in normal tissues, and decreased expression of HOXD8 was associated with increased tumor grade and stage, and lymph node metastasis." (PMID 36387262, 2022). "Intriguingly, we found that the mRNA and protein levels of HOXD8 were downregulated in ccRCC than that in normal tissues, and decreased expression of HOXD8 was associated with increased tumor grade and stage, and lymph node metastasis." (PMID 36387262, 2022). "Protein encoded by HOXD8 gene is a conserved transcription factor that exert a tumor-suppressing role in various tumors through diverse mechanism." (PMID 36387262, 2022). "This cluster was enriched in genes involved in differentiation and developmental processes (for example, SOX1 and SOX9, HOXD3 and HOXD8, and TBX4) and genes implicated as tumor suppressors (for example, SOX1 and SOX17, TSHZ3, WT1-AS, and FGF14)." (PMID 40931149, 2025). "All these genes are either involved in the regulation of MAPK and PI3K/AKT signaling pathways in addition to serving as tumor suppressors affecting drug resistance in other cancers including Homeobox protein Hox-D8 (HOXD8) and Paired Box 5 (PAX5)." (PMID 38275910, 2024). "This study provides evidence that overexpression of HOXD8 inhibits the proliferation of CRC cells and enhances their chemosensitivity, confirming that HOXD8 acts as a tumor suppressor in CRC." (PMID 38263157, 2024). "It was also revealed that, contrary to the tumorigenic property of HOXB7, HOXD8 was considered a tumor suppressor gene." (PMID 37174125, 2023). "According to the ceRNA mechanism, LINC00969 and HOXD8 are lowly expressed in BC and play an anti-tumor role." (PMID 38130932, 2023). "HOXD8 belongs to a homeobox family of genes and has a tumour suppressing role in different cancers by inducing apoptosis and inhibiting proliferation." (PMID 37245199, 2023). "Two of the identified homeobox genes in our current study, HODX1 and HOXD8, have been shown to play a tumor-suppressor function in various cancers." (PMID 34944472, 2021). "In this study, we proved that inhibiting HOXD8 hampered BCa cell proliferation, migration, invasion, and EMT, revealing HOXD8 as a tumor-facilitator in BCa." (PMID 33311496, 2020). "Taken together, it is reasonable to speculate that HOXD8 might be a tumor suppressor gene in ccRCC and a potential predictor of tumor progression." (PMID 36387262, 2022). "HOXD8 might be a tumor suppressor gene in ccRCC and a potential predictor of tumor progression." (PMID 36387262, 2022). "However, HOXD8 mRNA up-regulation was associated with decreased disease-free survival (DFS) compared to tumours without altered mRNA expression." (PMID 30194340, 2018). "It was observed that HOXD8 overexpression diminishes the phosphorylation of AKT and mTOR, which further inactivates the AKT/mTOR signaling pathway and decreases tumor growth and proliferation." (PMID 37174125, 2023). "The transcript levels of HOXB1, HOXA7, HOXB5, HOXD8, HOXB9, HOXA9, and HOXA11 were significantly lower in ccRCC tumor tissues compared to adjacent normal tissues, which was consistent in both TCGA and ICGC cohorts." (PMID 36387262, 2022). "According to our results, HOXD8 hypermethylation is the best-performing biomarker to identify the presence of BTC regardless of tumour location." (PMID 35177798, 2022). "HOXD8, one of the eight HOX genes, might be a tumor suppressor gene in ccRCC and a potential predictor of tumor progression." (PMID 36387262, 2022). "Furthermore, the expression of HOXD8 was not significantly altered in tumor tissue samples compared to adjacent normal tissues (P > 0.05)." (PMID 38302924, 2024).
cancer (18 papers, 2013 to 2025). A tumor composed of atypical neoplastic, often pleomorphic cells that invade other tissues. "The best-performing biomarker (chr2:176993479-176995557), associated with HOXD8, a pivotal gene in cancer-related pathways, achieved 100% sensitivity and specificity in a new series of tissue and bile samples." (PMID 35177798, 2022). "Furthermore, HOXD8 is a downstream gene of certain miRNAs associated with various cancers through cell proliferation and apoptosis." (PMID 39944136, 2025). "We previously reported that HOXD8 expression was blocked in BC tissues, and overexpression of HOXD8 restricted the proliferation and metastasis of cancer cells by binding to the ILP2 promoter to regulate ILP2 expression (Wen, Chen & Fang, 2021)." (PMID 38130932, 2023). "Previously, HOXD8 has been certified to be involved in the progression of cancers, though its role varies with cancer types." (PMID 33311496, 2020). "As for Hoxd8, it has been reported to regulate the cell cycle and oncogenesis in several carcinomas." (PMID 32849838, 2020). "This implies that the loss of HOXD8 seen in CRC is crucial for EMT and cancer progression." (PMID 39858044, 2025). "This study increases the understanding of the complex role of HOXD8 in cancer, and the results may have important implications for the development of new therapeutic strategies for CRC." (PMID 38263157, 2024). "HOXD8 has been shown to either promote or inhibit cancer progression depending on the cancer type." (PMID 38263157, 2024). "Moreover, HOXD8 was inversely related to serine/threonine kinase 38 (STK38) and MYC, two genes related to cancer progression." (PMID 39858044, 2025). "Of the genes that were altered in all cancer subtypes, the expression of five matched all datasets (HOXC8, HOXC11, HOXD8, PROX1, SIX2), although the overlap was found when considering the expression in the majority of the subtypes as HOXC11 and PROX1 were downregulated in TN CSC." (PMID 28202042, 2017). "HOXD8 has never been reported to be involved in cancer initiation before, so this is the first report of cooperation between HOXD8 and MEIS1 in AML induction." (PMID 26606454, 2015).
HOXD8 also shares sentences with these, for which no sentence is quoted: hepatocellular carcinoma (2 papers); prostate carcinoma (2); anencephaly (1); benign tumours (1); cervical cancer (1); glioblastoma (1); infection (1); insulinoma (1); lung diseases (1); melanoma (1); Müllerian agenesis (1); non-small cell lung carcinoma (1); oesophageal adenocarcinoma (1); ovarian diseases (1); pancreatic adenocarcinoma (1); pancreatic cancer (1); polycystic kidney disease (1); Sepsis (1); squamous cell carcinoma (1).